HLA-G (major histocompatibility complex, class I, G)
Diseases named in the same sentence as HLA-G in open-access papers (continued):
Sharing a sentence is not in itself a finding about the gene and the disease.
COVID-19 (continued). "Overall, HLA-G levels decreased during the replication phase of COVID-19 and increased again after clearance, likely relating to corresponding cytokine levels." (PMID 34578436, 2021). "In this scenario, HLA-G/receptor signalling among various immune cells is important in COVID-19 pathogenesis and progression." (PMID 34938296, 2021). "More evidence can be accumulated to solidify the basic and clinical aspects of HLA-G in COVID-19 progression and outcome." (PMID 34938296, 2021). "With this clinical trial, further understanding of the significance of HLA-G and its receptors in COVID-19 patients can be expected." (PMID 34938296, 2021). "and (d) Given HLA-E-CD94/NKG2A axis plays critical roles in COVID-19 and HLA-E cell surface expression depends other leader sequence peptides, particularly derived from HLA-G, what is the relationship between HLA-G and HLA-E expression?" (PMID 34938296, 2021). "In addition, a remarkable decrease in HLA-G+ immune cell numbers and exhaustion of host cellular immune responses are commonly observed in patients with severe COVID-19 illness." (PMID 37342325, 2023). "Moreover, in a study following the dynamic of HLA-G expression on various immune cells in a COVID-19 patient up to the convalescence phase, a high-low-high pattern of HLA-G was observed, most likely reflecting the SARS-CoV-2 infection dynamics." (PMID 35757770, 2022). "The use of pathogens, such as Plasmodium falciparum, as immune modulators for other infections could be extended for the modulation of membrane-bound HLA-G in COVID-19-infected tissues." (PMID 35204759, 2022). "In this study, we observed that lung biopsies from COVID-19-diseased patients displaying increased HLA-G protein expression exhibit lower miR-744-5p and miR-152 expression levels suggesting a deregulated HLA-G-specific miRNA expression due to COVID-19 infection." (PMID 36334153, 2022). "The presence of HLA-G, as an important immune check point, might suggest the use of Immune-Checkpoint Inhibitors (ICIs) against this molecule in COVID-19 treatment." (PMID 35204759, 2022). "There exist a number of publications on the immune cell repertoire and/or its spatial distribution in COVID-19 damaged lungs ranging from macroscopic to single-cell level, but a correlation between HLA-G expression, the immune cell composition, and the clinical course has not yet been described." (PMID 36334153, 2022). "Current available studies on HLA-G expression in patients with COVID-19." (PMID 34938296, 2021). "We hypothesise that cell surface HLA-G and circulating soluble HLA-G levels are related to the severity, outcome, or viral load in patients with COVID-19." (PMID 34938296, 2021). "The negative correlation between HLA-G expression and COVID-19 course underlines that HLA-G might be a potential therapeutic target in this disease." (PMID 36334153, 2022). "We hypothesise that HLA-G expression is related to cytokines in patients with COVID-19." (PMID 34938296, 2021). "However, the clinical significance of HLA-G and its receptor expression on immune cells among patients with COVID-19 remains largely unknown." (PMID 34938296, 2021). "The author still suggested that the follow-up of soluble HLA-G could be used to identify a worse prognostic of COVID-19 among patients with high levels of soluble HLA-G, and therefore the blocking of HLA-G interaction with their receptors may enhance immune response." (PMID 33584667, 2020). "This study aims to investigate the potential impact of HLA-E, HLA-G, and KIR genotypes on the severity of COVID-19, providing insights into the role of genetic determinants in immune response, disease progression, and individual susceptibility." (PMID 40391199, 2025). "Protein-protein interaction analysis of the effects exerted by anti-COVID-19 vaccination revealed one cluster comprised mainly of various HLA types, i.e., HLA-DOB, HLA-F, HLA-G, and ISG20." (PMID 39744634, 2024).
COVID-19 (continued). "Haplotype frequencies observed at the HLA-G 3’UTR polymorphic sites in population group controls and COVID-19 patients." (PMID 37342325, 2023). "In our case report, the dynamics of HLA-G and expression of its receptors ILT-2, ILT4, and KIR2DL4 on peripheral immune cell subpopulations in a critical COVID-19 case to convalescence were analysed." (PMID 34938296, 2021). "Several proteins related to inflammation and immune function, such as CXCL14 and soluble HLA-G (sHLA-G), have been identified by comparing patients with and without COVID-19." (PMID 38575325, 2024). "Our first consideration is that the HLA-G genetic structure between COVID-19 patients and the controls does not differ significantly." (PMID 37342325, 2023). "In most of the studies conducted to date, the attention has focused mainly on the expression of HLA-G and serum levels of the molecule in patients with severe COVID-19, rather than the genetic basis from which these manifestations result." (PMID 37342325, 2023). "All these tissue samples lacked HLA-G expression (data not shown) suggesting a tissue-specific HLA-G neo-expression upon course of COVID-19." (PMID 36334153, 2022). "The inhibition of neutrophil adhesion to endothelial cells obtained with plasma samples from survivor COVID-19 patients was significantly inhibited by anti-CD160 treatment, suggesting a role of HLA-G/CD160 interaction in regulating neutrophil adhesion to endothelial cells." (PMID 34578436, 2021). "However, researchers have mainly focused on HLA-G expression and serum levels in COVID-19 patients, rather than focusing on the genetic basis of these manifestations." (PMID 37342325, 2023). "Likewise, increased HLA-G levels have been found in infections of HIV-1, human cytomegalovirus, HPV, and herpes simplex virus-1, likely as a way to avoid immune detection of infected cells, and recently in patients with severe COVID-19." (PMID 34578436, 2021). "Despite HLA-G has been suggested to have immune regulatory functions in SARS-CoV-2-infected patients, a thorough analysis of HLA-G in COVID-19 patients is still lacking." (PMID 36334153, 2022). "In addition, a negative correlation between the expression of HLA-G, the nucleocapsid, and the spike protein was detected, which point to an altered expression of these molecules during the disease and indicate an up-regulation of viral proteins in the early phase of COVID-19." (PMID 36334153, 2022). "Through no specific mechanism for HLA-G up-regulation has been outlined during the SARS-CoV-2 infection, COVID-19 patients peripheral circulation highly increased cytokines such as IL-10, GM-CSF and IDO could be factors involved in the HLA-G expression modification." (PMID 34938296, 2021).
lung carcinoma (20 papers, 2012 to 2025). "HLA-G soluble protein is significantly associated with patients with metastatic tumor and can be used as a prognostic marker of lung cancer." (PMID 34868081, 2021). "Remarkably, all studies using HGY as HLA-G-detecting mAbs concluded that tumour HLA-G expression was significantly associated with shorter OS in breast, colorectal, esophageal, gastric and lung carcinoma patients." (PMID 34361031, 2021). "Aberrant HLA-G expression has been observed in lung cancer tissue and relatively high blood soluble HLA-G (sHLA-G) levels have been associated with lung cancer and advanced clinical disease stages." (PMID 27517300, 2016). "Adjusted OR (CI) for the associations between selected HLA-G genotypes and lung cancer and disease stages." (PMID 27517300, 2016). "Several studies have reported elevated HLA-G expression in a variety of cancers, including lymphomas, lung cancer, and CRC." (PMID 41234446, 2025). "Previous studies have demonstrated HLA-G expression in lung cancer tissue and relatively high blood sHLA-G levels in patients with NSCLC." (PMID 27517300, 2016). "Analysis of SPAG9 and HLA-G expression in parental CRUK0748-XCL cells revealed that both SPAG9 and HLA-G are expressed in parental CRUK0748-XCL, signifying that HLA-G and SPAG9 are expressed in primary lung cancer cells with a high predisposition to BM." (PMID 36780531, 2023). "It remains to be elucidated whether the expression of HLA-G in the context of lung cancer depends on the grade/type of tumor or genetic background of patients or both." (PMID 27517300, 2016). "However, the link between HLA-G alleles and lung cancer has not yet been studied." (PMID 27517300, 2016).
systemic lupus erythematosus (20 papers, 2010 to 2025). An autoimmune multi-organ disease typically associated with vasculopathy and autoantibody production. "This is particularly important for rheumatological diseases associated with RPL because HLA-G expression seems to be involved also in Systemic Lupus Erythematosus (SLE) and Antiphospholipid Syndrome (APS) pathogeneses." (PMID 36768880, 2023). "Comparative studies have demonstrated that HLA-G expression is significantly altered in patients with systemic lupus erythematosus (SLE) compared to healthy individuals." (PMID 41311648, 2025). "In many autoimmune disorders, including celiac disease, rheumatoid arthritis, lupus, psoriasis, and diabetes, HLA-G upregulation is related to disease onset and progression." (PMID 34578436, 2021). "There were also significantly higher soluble HLA-G levels in the circulating blood of patients with systemic lupus erythematosus." (PMID 34201301, 2021). "These genotype-dependent profiles suggest the potential utility of integrated immunogenomic signatures in guiding personalised therapeutic strategies, particularly interventions targeting trogocytosis, immune checkpoint modulation, and HLA-G–mediated tolerance in lupus." (PMID 41311648, 2025). "Interestingly, in patients with systemic lupus erythematosus, the UTR-1 haplotype that contains all variation sites reported to be associated with high production of HLA-G has also been associated with protection against disease development." (PMID 24204558, 2013). "This mini-review critically evaluates the mechanistic role of trogocytosis in modulating HLA-G expression and its implications for systemic lupus erythematosus (SLE) pathogenesis." (PMID 41311648, 2025).
glioblastoma (18 papers, 2012 to 2025). The most malignant astrocytic tumor (WHO grade IV). "Thus −966 G/A polymorphism could contribute to the magnitude of HLA-G expression during pregnancy and cancer, more particularly glioblastoma." (PMID 27577073, 2016). "In summary, the data indicate that activation through NKG2C is involved in the subtle tuning of NK cell reactivity towards glioblastoma cells expressing HLA-E and HLA-G." (PMID 35628668, 2022). "NKG2C+ NK cells exhibited natural cytotoxicity against HLA-ABC+/HLA-E+/HLA-G+ primary glioblastoma cells which was increased by KIR:HLA mismatch, whereas corresponding fresh NK cells from peripheral blood and NKG2A+ NK cells showed no cytotoxic response." (PMID 35628668, 2022). "In our study, we corroborated for the first time, a natural and specific cytotoxicity of NKG2C+ NK cells towards HLA class I-positive glioblastoma cells expressing HLA-E and HLA-G." (PMID 35628668, 2022). "In the context of glioblastomas, HLA-G expression was demonstrated to be influenced or regulated by environmental factors, particularly hypoxia or cytokines." (PMID 32922387, 2020). "Strikingly, it was demonstrated that only 10% of glioblastoma cells expressing HLA-G were sufficient to inhibit the PBMCs alloresponse against the whole tumor." (PMID 32922387, 2020). "A study by our group showed higher rates of soluble HLA-G expression in multiform glioblastomas than in meningiomas." (PMID 32903787, 2020). "Comparisons between these groups showed that HLA-G plasma expression in meningiomas was significantly lower than in multiform glioblastomas, admittedly the most aggressive of adult primary brain tumors." (PMID 32903787, 2020). "Hypoxic microenvironment plays also a key role in the progression of glioblastoma, a very aggressive tumor, in which HLA-G over-expression was well documented." (PMID 28781970, 2017). "Recently, the impact of hypoxic stress in HLA-G expression in U251MG glioblastoma cell line was explored." (PMID 28781970, 2017). "HLA-G tissue expression is very restricted but induced in numerous malignant tumors such as glioblastoma, contributing to their immune escape." (PMID 27577073, 2016). "In addition, glioblastoma cells express HLA-G, which is known to inhibit killing by NK cells in vitro and has broad immunosuppressive activities in vivo." (PMID 33753869, 2022). "In particular, in glioblastoma the expression of both HLA-E and HLA-G might be exploited for an immunotherapy with adaptive NKG2C+ NK cells, which specifically recognize HLA-E molecules presenting a high affinity peptide derived from HLA-G." (PMID 35628668, 2022). "In conclusion, our results support that HLA-G could be involved in glioblastoma evasion to antiangiogenic therapy, since de novo acute hypoxic stress will lead to HIF-1 stabilization and then binding to the exon 2 HRE." (PMID 27577073, 2016). "Moreover, we recently demonstrated that HLA-G expression may be upregulated in grade IV glioblastoma, a very aggressive tumor in which hypoxic microenvironment plays a key role in the disease progression." (PMID 27577073, 2016). "In glioblastoma, non-classical human leucocyte antigen E (HLA-E) and HLA-G are frequently overexpressed." (PMID 35628668, 2022). "Indeed, authors have hypothesized that in glioblastoma cells in hypoxic microenvironment culture conditions, CpG methylation in HIF target sites (5′RCGTG-3′) could moderate the observed HLA-G mRNA induction." (PMID 28781970, 2017).
multiple sclerosis (17 papers, 2010 to 2023). A progressive autoimmune disorder affecting the central nervous system resulting in demyelination. "Another disease in which the HLA-G molecule is implicated is Multiple Sclerosis (MS), the most common disabling neurological disorder in young adults." (PMID 35154112, 2022). "Additionally, the presence of HLA-G gene polymorphisms in patients with multiple sclerosis significantly correlates with the incidence of the disease." (PMID 34948145, 2021). "On the other hand, in humans, induced brain expression of HLA-G has been reported during the course of inflammatory diseases such as multiple sclerosis and has been associated with inhibition of responses mediated by cytotoxic T cells, NK cells, and inhibition of T cell proliferation." (PMID 24829926, 2014). "Because of the tolerogenic function of HLA-G in DCs, some works have tried to use these cells as a therapeutic approach to induce tolerance in some pathologies, such as multiple sclerosis." (PMID 35154112, 2022). "In contrast with these observations, data obtained in multiple sclerosis patients suggested that HLA-G and HLA-E can co-operate in the resolution of inflammation." (PMID 25202308, 2014). "Recent studies have demonstrated that HLA-G is induced with the development of inflammatory pathologies such as myositic lesions, psoriatic lesions on skin, and multiple sclerosis." (PMID 22654952, 2012). "A role for HLA-G in multiple sclerosis pathogenesis was first proposed based on the observation that sHLA-G levels were elevated in MS patients relative to healthy controls." (PMID 20593013, 2010). "While HLA-G expression is typically restricted to specific tissues, its expression can be induced under various pathological conditions, including cancer, transplantation, multiple sclerosis, inflammatory diseases, and viral infections." (PMID 37627278, 2023). "HLA-G has been described as a molecule involved in tissue protection against inflammatory aggression and its expression has been described in several inflammatory conditions, including multiple sclerosis, inflammatory bowel disease, RA and juvenile idiopathic arthritis." (PMID 25853899, 2015). "However, data obtained from our group in patients with juvenile idiopathic arthritis (JIA) and multiple sclerosis suggest that HLA-G and -E may have either an opposite or a synergistic role in the course of these pathological conditions." (PMID 25202308, 2014). "In multiple sclerosis patients, LILRB2 and HLA-G are co-expressed on central nervous system cells and in areas with microglia activation, while HLA-G expression is barely detectable in healthy controls." (PMID 34737739, 2021).